KRT3 (keratin 3)
Description:
Structural component of intermediate filaments in the corneal epithelium. Forms heteropolymers with the type I keratin KRT12, assembling into keratin intermediate filament networks that provide mechanical strength and structural integrity to the corneal epithelial layer.
Synonyms: K3; CK3; MECD2
Tractability: PROTAC: ubiquitination databases record sites on it.
Gene: Protein-coding gene on chromosome 12 (52,789,685 to 52,796,117, reverse strand). Ensembl gene ENSG00000186442.
Pathways (Reactome):
Developmental Biology: Formation of the cornified envelope; Keratinization
Gene Ontology:
Molecular function: protein binding; structural constituent of skin epidermis
Biological process: intermediate filament cytoskeleton organization; epithelial cell differentiation; intermediate filament organization; keratinization
Cellular component: extracellular exosome; cytosol; intermediate filament; keratin filament
Genetic constraint (gnomAD): Loss-of-function variants: 31 observed, 42.01 expected, observed/expected ratio (o/e) 0.74, 90% interval 0.55 to 1. The upper end of that interval is the gene's LOEUF score, 1, which puts it in group 4 of 6, group 1 being the genes least tolerant of losing a copy. Missense variants: 805 observed, 813.53 expected, observed/expected ratio (o/e) 0.99, 90% interval 0.93 to 1.05. Synonymous variants: 359 observed, 326.99 expected, observed/expected ratio (o/e) 1.1, 90% interval 1.01 to 1.2.
Homologues: Orthologues: chimpanzee KRT3 (99% identical), macaque KRT3 (93% identical), pig KRT3 (86% identical), rabbit KRT3 (82% identical), dog KRT3 (81% identical), guinea pig KRT3 (78% identical). Paralogues in human: KRT76 (77% identical), KRT1 (61% identical), KRT5 (61% identical), KRT2 (60% identical), KRT6A (60% identical), KRT6B (60% identical), KRT6C (59% identical), KRT4 (57% identical), KRT75 (55% identical), KRT79 (55% identical), KRT77 (52% identical), KRT73 (52% identical), and 56 more.
Diseases named in the same sentence as KRT3 in open-access papers:
KRT3 is named in the same sentence as 22 diseases in open-access papers, as found by Europe PMC text mining. Sharing a sentence is not in itself a finding about the gene and the disease. The quoted sentences say what the papers report.
corneal dystrophies (6 papers, 2009 to 2025). "Background/Objectives: to report a novel KRT3 Meesmann corneal dystrophy (MECD) mutation and its clinical findings in a Spanish family, thus completing the international database." (PMID 39941522, 2025). "Although mutations in genes such as KRT3, KRT12, PIP5K3, TGFBI, and UBIAD1 have been associated with specific corneal dystrophies, genes associated with all corneal dystrophies have yet to be identified." (PMID 32823625, 2020).
Meesmann corneal dystrophy (6 papers, 2008 to 2026). Meesmann corneal dystrophy (MECD) is a rare form of superficial corneal dystrophy characterized by distinct tiny bubble-like, round-to-oval punctate bilateral opacities in the central corneal epithelium, and to a lesser extent in the peripheral cornea, with little impact on vision. "In conclusion, this study provides the first evidence that the co-occurrence of variants in two Meesmann corneal dystrophy-associated genes (KRT3 and KRT12) can jointly account for the disease phenotype." (PMID 41683752, 2026). "Meesmann epithelial corneal dystrophy (MECD) is a rare autosomal dominant disorder caused by dominant-negative mutations within the KRT3 or KRT12 genes, which encode the cytoskeletal protein keratins K3 and K12, respectively." (PMID 26758872, 2016). "Krt8/keratin 8 was shown to protect against degeneration of retinal pigment epithelium under oxidative stress, and KRT3 and KRT12 gene mutations associated with Meesmann corneal dystrophy." (PMID 35118070, 2021). "All known mutations in the cornea specific genes KRT3 and KRT12 are responsible for the development of Meesmann`s corneal dystrophy, an autosomal dominant disorder of the corneal epithelium." (PMID 20577595, 2010). "The only known disorder associated with mutation in cornea-specific keratin 3 (KRT3) and keratin 12 (KRT12) representing type II and I intermediate filaments, respectively, is Meesmann corneal dystrophy (MCD)." (PMID 18806880, 2008).
pterygium (2 papers, 2022 to 2025). A wedge-shaped fibrovascular lesion arising from the bulbar conjunctiva and extending to the cornea. "Since EBMD, SND and pterygium lead to changes in the corneal epithelium, we analyzed levels of the corneal keratins KRT3 and KRT12, as well as the conjunctival keratin 13 (KRT13) in our samples." (PMID 40094891, 2025). "In this context, we compared the expression of corneal keratins KRT3, KRT12, and KRT13 in EBMD, SND, and pterygium." (PMID 40094891, 2025).
aniridia (1 paper, 2021). Aniridia is a congenital ocular malformation characterized by the complete or partial absence of the iris. "KRT3 and KRT12 markers are downregulated in ocular surface of subjects with aniridia and are described as being regulated by PAX6 in vitro as well." (PMID 34827649, 2021).
dominant retinitis pigmentosa (1 paper, 2016). "Of which, three variants (ATXN1:NM_000332:p.E357K, TCF4:NM_001243226:c.1793-5G > A and KRT3:NM_057088:c.1189-5T > C) are known pathogenic variants of dominant retinitis pigmentosa." (PMID 27391953, 2016).
glaucoma (1 paper, 2023). Increased pressure in the eyeball due to obstruction of the outflow of aqueous humor. "We identified multiple genes of interest with higher relative expression in glaucoma-related cell types; examples include NEFM, SYT2 expression in RGCs, AQP5 and KRT3 expression in corneal epithelial cells and CDH6 in ciliary muscle." (PMID 36833422, 2023).
lattice corneal dystrophy (1 paper, 2023). "Almost all the variants in KRT3 caused MECD, except for a sporadic case with c.1492G>A, p.(Glu498Lys), which presented MECD co-existing with lattice corneal dystrophy (LCD)." (PMID 36902444, 2023).
KRT3 also shares sentences with these, for which no sentence is quoted: infection (6 papers); tumor (6); keratoconus (3); Astigmatism (1); breast carcinoma (1); breast tumor (1); Burkholderia Infections (1); cancer (1); Corneal opacity (1); hearing loss (1); hepatocellular carcinoma (1); schizophrenia (1); toxoplasmosis (1); urinary tract infection (1); viral infections (1).